SNORD62 (Small nucleolar RNA SNORD62 )
Synonyms: LOC124902338
Gene: Small nucleolar RNA gene on chromosome 9 (137,094,345 to 137,094,430, forward strand). Ensembl gene ENSG00000199411.
Gene Ontology:
Biological process: RNA processing
Cellular component: nucleolus
Homologues: Orthologues: chimpanzee SNORD62 (98% identical), macaque SNORD62 (91% identical), guinea pig SNORD62 (80% identical), mouse Gm25632 (80% identical), rat SNORD62 (80% identical), mouse Gm24920 (79% identical), tropical clawed frog SNORD62 (65% identical), tropical clawed frog SNORD62 (63% identical), tropical clawed frog SNORD62 (57% identical). Paralogues in human: SNORD62A (85% identical), SNORD62B (85% identical).
Diseases named in the same sentence as SNORD62 in open-access papers:
SNORD62 is named in the same sentence as 1 disease in open-access papers, as found by Europe PMC text mining. Sharing a sentence is not in itself a finding about the gene and the disease. The quoted sentences say what the papers report.
cancer (1 paper, 2021). A tumor composed of atypical neoplastic, often pleomorphic cells that invade other tissues. "The combination of miRNA (miR-142-3p), mRNAs (CXCL5, KIF2A, RGS18, APL6IP5, and DAPP1), and snoRNAs (SNORD17, SCARNA12, SNORA6, SNORA12, SCRNA1, SNORD97, SNORD62, and SNORD38A) clearly distinguished the normal samples from the cancer group samples." (PMID 34827689, 2021).